SNORA80E (small nucleolar RNA, H/ACA box 80E)
Synonyms: ACA42; SNORA42
Gene: Small nucleolar RNA gene on chromosome 1 (155,919,909 to 155,920,045, reverse strand). Ensembl gene ENSG00000207475.
Gene Ontology:
Biological process: RNA processing
Cellular component: nucleolus
Homologues: Orthologues: chimpanzee SNORA80E (98% identical), macaque SNORA80E (96% identical), pig SNORA80E (91% identical), rabbit SNORA80E (88% identical). Paralogues in human: SNORA80A (75% identical), SNORA80B (74% identical), SNORA80C (74% identical), SNORA80D (73% identical).
Diseases named in the same sentence as SNORA80E in open-access papers:
SNORA80E is named in the same sentence as 16 diseases in open-access papers, as found by Europe PMC text mining. Sharing a sentence is not in itself a finding about the gene and the disease. The quoted sentences say what the papers report.
lung carcinoma (16 papers, 2014 to 2024). "From the profiling studies, SNORA80E (also termed SNORA42 or ACA42) emerged as a recurrent overexpressed H/ACA box snoRNA in many independent signatures of lung cancer, both in tissue and fluid biopsies." (PMID 32111002, 2020).
non-small cell lung carcinoma (10 papers, 2014 to 2021). A group of at least three distinct histological types of lung cancer, including non-small cell squamous cell carcinoma, adenocarcinoma, and large cell carcinoma. "Recently it was show that SNORA80E (also denoted SNORA42) is an emerging oncogene in colorectal cancer and in non-small cell lung cancer tumorigenesis." (PMID 31506436, 2019).
SNORA80E also shares sentences with these, for which no sentence is quoted: tumor (12 papers); cancer (8); colorectal cancer (8); prostate carcinoma (3); breast carcinoma (2); acute leukemia (1); acute promyelocytic leukemia (1); colon cancer (1); gastric cancer (1); gastric tumors (1); hepatoma (1); metastatic prostate carcinoma (1); plasma cell dyscrasias (1); squamous cell carcinoma (1).